CD14 (CD14 molecule)
Diseases named in the same sentence as CD14 in open-access papers (continued):
Sharing a sentence is not in itself a finding about the gene and the disease.
autoimmune disease (31 papers, 2008 to 2025). A disorder resulting from loss of function or tissue destruction of an organ or multiple organs, arising from humoral or cellular immune responses of the individual to their own tissue constituents. "Our results provide for the first time evidence for differential expression of several MHC Class II genes in whole blood, PBMCs, CD4+ T cells, CD8+ T cells, and CD14+ monocytes of individuals with genetic predisposition to an autoimmune disease, i.e. RA." (PMID 34484204, 2021). "The genetic polymorphisms of CD14 have been confirmed to be associated with a variety of autoimmune diseases." (PMID 30700980, 2018). "Additionally, B cells (P = 3.7 × 10−48) and monocytes (P = 1.4 × 10−41) were involved in multiple trait pairs within the Blood/immune category, with mitochondrial DNA (mtDNA) from CD14 + monocytes closely associated with autoimmune diseases." (PMID 41212883, 2025). "Notably, HLA-DR + monocytes (especially CD14 + monocytes) had an OR greater than 1 for all three autoimmune diseases, suggesting their importance in increasing disease risk." (PMID 40254686, 2025). "The results revealed that HLA-DR + monocytes, especially CD14 + monocytes, had OR greater than 1 for all three autoimmune diseases, suggesting these cells may increase disease risk." (PMID 40254686, 2025). "CD14+ cells were reported to play an essential role in inflammation and infection, which contribute to the development of the autoimmune diseases." (PMID 36744920, 2023). "Overall, the results suggest that the process of anaesthesia/surgery shows a higher impact on the CD14+ monocytes of patients with autoimmune diseases." (PMID 35061932, 2022). "Conversely, CD14 reduces the severity of intestinal lesions and ulcerations, demonstrating its protective role in autoimmune diseases." (PMID 34458379, 2021). "More interestingly, enrichment of PI3K pathway was found in CD14+ monocytes in both of these autoimmune diseases." (PMID 34079550, 2021). "CD14+ monocytes are important components of innate immune response, and take part in the immunopathogenesis of autoimmune disorders, cancers, and infectious diseases." (PMID 32276581, 2020). "As an important component of innate immunity, alterations in CD14 expression appear to correlate with aberrant immune responses and autoimmune diseases." (PMID 30700980, 2018). "Consistently, our gene-disease association study denoted that CD14 is involved in many immunological diseases such as HIV infections, inflammation and some autoimmune diseases." (PMID 27878450, 2017). "Since CD14 plays a role in the pathogenesis of autoimmune diseases, further research is necessary." (PMID 39409006, 2024). "Interestingly, the migratory capacity of CD209+/CD14+ dendritic cells has been shown to be significantly inhibited by a JAK/STAT pathway inhibitor (tofacitinib) used in the treatment of various autoimmune diseases." (PMID 38275392, 2023). "Non-classical monocytes (CD14+CD16+) have been associated with various autoimmune diseases and contribute to blood–brain barrier (BBB) breakdown." (PMID 36536441, 2022). "Moreover, altered proportions and conversion of monocyte subsets CD14+/CD16– into CD16+ occur in most autoimmune diseases." (PMID 28245863, 2017). "This study reports that Activin A, a protein abundantly produced in the skin during normal and pathological wound healing and inflammatory/autoimmune diseases (this study), induces the differentiation of human CD14+ monocytes in Langerin+, Birbeck granules+, E-cadherin+, CLA+ and CCR6+ cells." (PMID 18813341, 2008). "In autoimmune disorders, the expansion of ABCs and CD14+ Atypical B cells is significantly higher; therefore, conditional targeting of the transcription factor T-bet encoded by TBX21, which is important and sufficient for ABCs formation, could be an efficient and novel therapeutic target." (PMID 36544777, 2022).
autoimmune disease (continued). "In this respect, increased numbers of CD14-expressing monocytes, CD68 or CD163-expressing macrophages, CD1c or CD11c-expressing myeloid dendritic cells have been documented in different autoimmune diseases." (PMID 24740301, 2014). "CX3CR1 levels were also not significantly different in sorted CD5−CD163+CD14-positive and CD14-negative DC3s from patients with autoimmune diseases, further indicating that CX3CR1 expression in CD1c+ DCs may be independent from CD14 expression in CD1c+ DCs." (PMID 37042831, 2023). "Previous studies have shown that both CD14+ and CD14dim monocytes can produce cytokines TNF‐α, IL‐1β, and type I interferon under various conditions such as infection, inflammatory and autoimmune diseases, and cytokine‐release syndrome, though different signaling pathways may be involved." (PMID 35347900, 2022).
Crohn disease (31 papers, 2012 to 2024). A gastrointestinal disorder characterized by chronic inflammation involving all layers of the intestinal wall, noncaseating granulomas affecting the intestinal wall and regional lymph nodes, and transmural fibrosis. "NOD2/CARD15, TLR4 and CD14 mutations in Scottish and Irish Crohn's disease patients: evidence for genetic heterogeneity within Europe?" (PMID 28819537, 2017). "Polymorphisms in the CARD15/NOD2 gene, in addition to functional variants of the toll-like receptor-4 (TLR4) and CD14 genes, have been associated with the development of Crohn’s disease." (PMID 22605977, 2012). "Also recently, ALDH1A1 expression in intestinal CD14+ macrophages in tissue from patients with Crohn’s disease was linked to increased RA production and a more inflammatory phenotype." (PMID 25926859, 2014). "Although the biological effect of the CD14(-159C/T) polymorphism remains unclear, the SNP has been associated with several diseases such as TB, brucellosis, chronic peridonitis, chronic chlamydial infection and Crohn disease." (PMID 29281719, 2017). "Our findings were consistent with a previous report, which showed that CD14+ macrophages in Crohn’s disease consisted of IL-1β producing CD163−/dim cells." (PMID 37344477, 2023). "By means of exosomes, CD14+ macrophages promoted CD4+ T-cell activation-induced cell death resistance in Crohn’s disease." (PMID 37143656, 2023). "Proteobacteria and Pseudomonadales were also found to be significantly enriched in intestinal CD14+CD11c+ macrophage samples from Crohn’s disease patients." (PMID 37180436, 2023). "While defining an active molecular mechanism of immune evasion by pathogens, the interaction between FimH and CD14 represents a potential target to interfere with persistent and recurrent infections, such as urinary tract infections or Crohn’s disease." (PMID 35881547, 2022). "Other research also showed that Gammaproteobacteria are enriched within CD14+ macrophages from the intestinal lamina propria of patients with Crohn's disease vs. mucus." (PMID 36386696, 2022). "The pretreatment TREM-1 expression levels of CD14+ monocytes of Crohn’s disease (CD) patients were predictive of outcome to anti-TNF mAb therapy, with low TREM-1 expression associated with response to anti-TNF." (PMID 33790898, 2021). "It has also been associated to neutrophil count (P = 2.18 × 10−9) and monocyte CD14+ proportions (P = 4.72 × 10−13) in the blood, and these two cell subpopulations have been reported to be involved in the pathogenesis of Crohn’s disease." (PMID 34229738, 2021). "In the intestinal tract of Crohn’s disease, CD14+ macrophages are increased compared to normal intestine." (PMID 32076066, 2020). "In this report, the 16S rRNA gene amplicon sequencing method was used to identify bacteria that are specifically present in intestinal CD14+CD11c+ macrophages of Crohn’s disease patients." (PMID 32076066, 2020). "Alpha diversity of bacteria presented in CD14+CD11c+ macrophages and mucus in the intestinal mucosal lamina propria of Crohn’s disease patients was evaluated." (PMID 32076066, 2020). "We compared the gene expression of CD14+CD11c+CD163low and CD14−CD11c+ myeloid cells in intestinal lamina propria from surgically resected intestine of Crohn’s disease patients with normal intestine obtained as surplus intestinal sample of colon cancer." (PMID 32076066, 2020). "In contrast, the expression of genes related to the type 1 interferon signaling pathway was enhanced in Crohn’s disease CD14+CD11c+CD163low cells compared with normal CD14+CD11c+CD163low cells." (PMID 32076066, 2020). "First, in Crohn’s disease, we showed that the bacterial flora of CD14+CD11c+ macrophages in intestinal lamina propria differed in alpha diversity and homology from that of mucus." (PMID 32076066, 2020). "Bacteria present in intestinal CD14+CD11c+ macrophages and mucus of Crohn’s disease patients were separated into different clusters in principal coordinates analysis." (PMID 32076066, 2020).
Crohn disease (continued). "The accumulation of CD14+ macrophages in patients with Crohn’s disease has been attributed to an increased recruitment of inflammatory monocytes and a concomitant disruption of physiological, tissue-specific macrophage differentiation." (PMID 26475133, 2015). "It remains to be verified whether the bacteria found in the Crohn’s disease intestinal CD14+CD11c+ macrophage in this time are actually different in terms of persistence in macrophages and inflammation induction to macrophages." (PMID 32076066, 2020). "In the intestine of Crohn’s disease patients, CD14+CD11+CD163low macrophages contribute to inflammation through the induction of Th17 cells and production of inflammatory cytokines; the CD14+CD11c+163high fraction is anti-inflammatory through the production of IL-10 in normal cases." (PMID 32076066, 2020). "CD209+CD14+ cells were significantly increased in the lesion of lamina propria of Crohn's disease." (PMID 28377641, 2017). "Furthermore, CD14+CCR2+CX3CR1+ monocyte-derived intestinal MPs can elicit the activation of IFN-γ-producing CD3−CD56+NKp46+NKp44− group 1 ILCs from Crohn's disease patients." (PMID 26269452, 2015). "Moreover, a very recent study shows that CD172a+ slanDCs in Crohn's disease tissues express CD14." (PMID 26695549, 2016). "However, CD14+CD16+ monocytes also express CCR2 and are associated with Crohn’s disease and CVD." (PMID 24398220, 2014). "CD14/CD16 monocytes represents a major proinflammatory immune cell population in IBD in general and in Crohn’s disease specifically." (PMID 30373293, 2018). "Crohn′s disease patients treated with the non-biological treatment exhibited 2.3-fold decreased percentage of non-classical CD14+CD16++ monocytes in comparison to patients treated with biological therapy." (PMID 36010364, 2022). "Crohn′s disease patients treated with NBT showed decreased percentage of non-classical CD14+CD16++ monocytes, whereas patients with biological therapy remained at the control level." (PMID 36010364, 2022). "Decreased percentage of anti-inflammatory non-classical CD14+CD16++ monocytes in non-biologically treated Crohn’s disease and their unchanged level after biological therapy indicate the higher potential of intestinal wound healing in biologically treated patients." (PMID 36010364, 2022). "We, and others, have shown that CD14+CD16+, but not CD14dimCD16+, monocytes are markedly enhanced at sites of inflammation in chronic autoimmune disorders such as RA and Crohn’s diseases." (PMID 25329467, 2014). "We can speculate that lower CD44 expression in CD44+CD14+ lymphocyte in blood after NBT, found in ulcerative colitis but not in Crohn’s disease, can be due to the higher naive B-cell count in ulcerative colitis." (PMID 36010364, 2022). "Patients with Crohn’s disease treated with non-biological therapy (NBT) exhibited a lower percentage of anti-inflammatory CD14+CD16++ monocytes, whereas NBT-treated patients with ulcerative colitis had lower expression of CD44 on CD14+CD44+ lymphocytes in comparison to controls, respectively." (PMID 36010364, 2022).
tuberculosis (31 papers, 2012 to 2025). A chronic, recurrent infection caused by the bacterium Mycobacterium tuberculosis. "The TLR4/CD14 complex is responsible for cytokine production via NF-κB, and the SNP CD14–159 in the promoter region has been associated with susceptibility to tuberculosis, and was shown to influence the production of IFN-γ." (PMID 28850598, 2017). "Soluble CD14 levels also have been shown to be influenced by CD14 polymorphisms in diverse populations such as infants, patients with cardiovascular disease, tuberculosis, periodontal disease and healthy persons." (PMID 28302109, 2017). "In a Turkish population the association between the CD14 -159C/T polymorphism and tuberculosis (88 patients vs. 116 control subjects) was investigated." (PMID 26793196, 2015). "The results of this meta-analysis suggest that CD14 -159C/T polymorphism is associated with a predisposition to the development of tuberculosis." (PMID 26793196, 2015). "CD14-159 C/T polymorphism was investigated in several populations with tuberculosis." (PMID 26793196, 2015). "Other reports have shown significant association of CD14 gene polymorphism with varying disease phenotypes, including monocyte surface expression in Canadian Holstein and Jersey cows during bovine mastitis, and in Chinese Holstein cows during bovine tuberculosis." (PMID 31963925, 2020). "Previously, rs1800796 (−572 C/G) of IL-6 was detected to be associated with adult TB and the regulatory effects of this SNP on IL-6 production in plasma and CD14+ monocyte cultures stimulated with a M. tuberculosis product were also conformed." (PMID 24772425, 2014). "Another scRNA-seq study of cell-sorted CD14+CD16+ monocytes from PBMCs of individuals with active tuberculosis defined six subpopulations within this subset, highlighting its complexity and diversity." (PMID 40051633, 2025). "In accordance with an earlier report, classical monocytes (Mono_CD14) exhibited significantly higher levels of inflammatory genes from the S100 family in tuberculosis patients who experienced relatively severe symptoms." (PMID 39135683, 2024). "In line with this, CD14‐expressing monocytes (e.g., Mono_CD14 and Mono_MDSCs) have been substantiated as major sources of inflammatory storm in other infectious diseases (e.g., tuberculosis and COVID‐19)." (PMID 39135683, 2024). "We also demonstrate that PD-1 and PDL-1 are highly expressed at the site of infection during human tuberculosis and that these molecules are involved in Mtb-specific cytotoxic killing of CD14+ targets cells from human pleura effusion (PE) samples." (PMID 30655556, 2019). "In Chinese population (432 Chinese patients with tuberculosis and 404 controls), two positions were analyzed: CD14 -1145 and CD14 -159." (PMID 26793196, 2015). "Cluster of differentiation 14 (CD14) gene is an important component of the human innate immune system and its role in tuberculosis (TB) has been sparsely documented." (PMID 23741383, 2013). "We also performed preliminary analysis of the cellular source of IL-10 and IL-22 and found both more frequently in CD14+ cells, consistent with increasing evidence that innate immune system activation is a component of the immunopathology of tuberculosis-IRIS." (PMID 23303806, 2013). "Lipopolysaccharide is recognized by TLR4 and CD14, and both are upregulated in melioidosis (P = 0.0016 and 1.5 × 10–6, respectively); however, TLR4 and CD14 are also upregulated in tuberculosis (P = 1.5 × 10–6 and 9.4 × 10–4)." (PMID 23383015, 2013). "A microarray profiling survey revealed that the expression of miRNAs derived from CD14+ monocytes of active pulmonary TB patients was downregulated, and nothing but miR-20a-5p expression could be conversed after successful anti-tuberculosis therapy." (PMID 35525953, 2022).
tuberculosis (continued). "The DEPRGs were particularly associated with Salmonella infection, Yersinia infection, tuberculosis, CLEC7A/inflammasome pathway, viral protein interaction with cytokine and cytokine receptor, transfer of LPS from LBP carrier to CD14, and neutrophil degranulation." (PMID 35991562, 2022). "TLR4 and CD14 are upregulated in both melioidosis and tuberculosis." (PMID 23383015, 2013). "Here, we identify PD-L1 expression on CD14- CD16+ monocytes as a critical determinant for preventing early tuberculosis (TB) progression." (PMID 41446278, 2025). "In fact, CD14+ expression has been reported as a marker of active tuberculosis, indicating its defense role against TB." (PMID 34680598, 2021). "Given the importance of monocytes in the innate immune response to tuberculosis, we investigated the profiles of monocyte subsets in ATB patients based on the expression of CD14 and CD16." (PMID 31779590, 2019). "We then observed that PD-L1 blocking enhanced Mtb-specific CD8+ T cell mediated killing of CD14+ PE cells, therefore highlighting the relevance of PD-1 pathway in CD8+ T cell-induced macrophage death during human tuberculosis." (PMID 30655556, 2019). "In addition, phagosome processes and tuberculosis disease were also significantly enriched, and AKT3, CD14, FCGR3A, and CORO1A were significantly up-regulated in the MAB group." (PMID 37764178, 2023). "Interestingly, phagosome processes and tuberculosis disease were also significantly enriched, with AKT3, CD14, FCGR3A, and CORO1A being significantly up-regulated in MAB-infected patients." (PMID 37764178, 2023). "In addition, we propose CD14, IL-1R, THBS1, MMP9 and FYVE as potential biomarkers of bovine tuberculosis." (PMID 22815916, 2012). "However, previous studies have shown that monocyte functionality may be impaired in active tuberculosis, with CD16+CD14+ monocytes refractory to dendritic cell maturation, leading to impaired antigen presentation and decreased secretion of IL-1β and IL-12." (PMID 28369200, 2017).